HOXA1 (homeobox A1)
Diseases named in the same sentence as HOXA1 in open-access papers (continued):
Sharing a sentence is not in itself a finding about the gene and the disease.
lung adenocarcinoma (6 papers, 2007 to 2022). A carcinoma that arises from the lung and is characterized by the presence of malignant glandular epithelial cells. "Likewise, HOXA1, found to be mutated in lung adenocarcinoma, is associated with a hypermethylation phenotype; hence, it might be targetable by DNA methyltransferase inhibitors, such as decitabine and azacitidine, suggesting a molecularly stratified treatment strategy for this patient population." (PMID 26438695, 2015). "However, it has been reported that high HOXA1 expression is correlated with cisplatin resistance of lung adenocarcinoma." (PMID 36119466, 2022). "Here we demonstrate that HOXA1 is a very promising DNA methylation marker for lung adenocarcinoma." (PMID 17967182, 2007). "The four most highly ranked loci, CDKN2A EX2, CDX2, HOXA1 and OPCML, which show significant DNA methylation even in stage IA tumor samples, merit further investigation as some of the most promising lung adenocarcinoma markers identified to date." (PMID 17967182, 2007). "To our knowledge, CDKN2A EX2, CDX2, HOXA1 and OPCML constitute the strongest lung adenocarcinoma DNA methylation markers identified to date, and we are working on further evaluations of their potential with great anticipation." (PMID 17967182, 2007). "Based on the results of our analyses, four loci that are very strong candidates for a DNA methylation panel aimed at early lung adenocarcinoma detection have been identified: CDKN2A EX2, CDX2, HOXA1 and OPCML." (PMID 17967182, 2007). "Thus, we suggest that CDKN2A EX2, CDX2, HOXA1 and OPCML are the top candidates from the 28 tested, and should be validated as DNA methylation markers for lung adenocarcinoma." (PMID 17967182, 2007). "Using the current tissue collection and 5-fold cross validation, the four most significant loci (CDKN2A EX2, CDX2, HOXA1 and OPCML) individually distinguish lung adenocarcinoma from non-cancer lung with a sensitivity of 67–86% and specificity of 74–82%." (PMID 17967182, 2007).
oral cancer (6 papers, 2012 to 2024). "The intersection of these oral cancer-related genes with our curated list of predicted and validated let-7c-5p targets resulted in three genes of interest: HOXA1, TAGLN, and TSPAN2." (PMID 39308508, 2024). "HOXA1, a member of homeobox genes superfamily, has been reported as a target of miR-494-3p in oral cancer." (PMID 27399693, 2016). "The present study is the first to report hypermethylation in the 3′UTR region of HOXA1, which may be directly correlated with increased expression in oral cancer." (PMID 38473236, 2024). "In healthy oral mucosa derived from patients without risk factors for oral cancer, only HOXA1, HOXA2 and HOXA4 were expressed, whereas the abundance of transcripts in histologically normal-looking oral mucosa near OSCC and in OSCC samples was higher." (PMID 22498108, 2012). "Differentially expressed microRNAs have been found to tightly regulate four of the possible biomarkers that we identified—HMGA2, EGFR, HOXA1, and ABCC5/ABCC4 —further supporting their involvement in oral-cancer progression." (PMID 26179909, 2015).
atherosclerosis (5 papers, 2021 to 2024). A disease characterized by the build-up of fatty material and calcium deposition in the arterial wall resulting in partial or complete occlusion of the arterial lumen. "Endothelial miR-10a/b showed low expression in regions susceptible to atherosclerosis accompanied by up-regulation of Homeobox A1 (HOXA1), an experimentally validated target of miR-10a." (PMID 39434104, 2024). "By targeting the homeobox A1 gene, miR-99a-5p acted as an atherosclerosis inhibitor, reducing lesion formation." (PMID 37697228, 2023). "In addition, miR-99a-5p attenuates atherosclerosis via targeting Homeobox A1 (HOXA1)." (PMID 39628814, 2024).
autism (5 papers, 2010 to 2024). Persistent deficits in social interaction and communication and interaction as well as a markedly restricted repertoire of activity and interest as well as repetitive patterns of behavior. "In studies pertaining to autism, researchers have discovered a correlation between the HOXA1 A218G polymorphism and variations in head circumference among autistic patients." (PMID 38311789, 2024). "Neuronal differentiation- and survival-associated genes, such as wingless-type MMTV integration site family member 2 (WNT2) and homeobox A1 (HOXA1) were also reported as autism susceptibility genes." (PMID 21935445, 2011). "A gene × gene interaction between HOXB1 and HOXA1 gene variants was initially proposed to contribute to autism." (PMID 20678259, 2010). "In our sample, the HOXA1 c.218A>G [His73Arg] polymorphism was significantly associated with autism, although we found an association with the A218 and not the G218 allele, in contrast to the original study." (PMID 20678259, 2010). "Genetic findings affecting this brain region in autism include the Homeobox A1 (HOXA1) gene which has been proposed as a candidate gene for ASD for over a decade, as it regulates embryological patterning of hind-brain structures implicated in autism neurobiology." (PMID 24278731, 2012). "An initial report, suggesting that HOXB1 could confer autism vulnerability in interaction with HOXA1, was not confirmed by five small association studies." (PMID 20678259, 2010).
hepatocellular carcinoma (5 papers, 2016 to 2024). A malignant tumor that arises from hepatocytes. "Recent research indicated that HOXA1 expression is markedly correlated with the overall survival of patients with hepatocellular carcinoma." (PMID 26791264, 2016). "HOXA1 has been reported to play an oncogenic role in hepatocellular carcinoma." (PMID 37528397, 2023).
leukemia (5 papers, 2012 to 2022). A malignant (clonal) hematologic disorder, involving hematopoietic stem cells and characterized by the presence of primitive or atypical myeloid or lymphoid cells in the bone marrow and the blood. "HOXA1 misexpression has been reported in leukemia, and carcinomas of the cervix, breast and oral cavity." (PMID 22498108, 2012). "Evidence shows that HOTAIRM1 is a critical regulator for the expression level of HOXA1 and HOXA4, which is involved in cell growth in leukemia cells." (PMID 30728826, 2018).
bladder cancer (4 papers, 2019 to 2023). "KDM3A was found to regulate the growth of bladder cancer cells and HOXA1 expression through the demethylation of H3K9me2." (PMID 37627900, 2023). "Meanwhile, the knockdown of HOXA1 suppressed the growth of bladder cancer cells." (PMID 37627900, 2023). "The mRNA expression levels of HOXA1 and KDM3A were significantly higher in bladder cancer tissues as compared to normal bladder tissues." (PMID 37627900, 2023). "Strikingly, KDM3A and HOXA1 exhibit strong correlations in bladder cancer tissues (n = 55) and cell lines (n = 18), further supporting that KDM3A contributes to bladder cancer progression by regulating HOXA1." (PMID 32354028, 2020).
head and neck squamous cell carcinoma (4 papers, 2015 to 2022). A squamous cell carcinoma that arises from any of the following anatomic sites: lip and oral cavity, nasal cavity, paranasal sinuses, pharynx, larynx, and salivary glands. "HOXA1 is a novel biomarker in the prognosis of head and neck squamous cell carcinoma." (PMID 36289596, 2022).
liver cancer (4 papers, 2015 to 2024). An epithelial or non-epithelial malignant neoplasm that arises from the liver. "Knockdown of circWHSC1 has been shown to suppress the proliferation and metastasis of liver cancer cell lines by regulating HOXA1." (PMID 38311789, 2024). "miRNA-99a has been shown to suppress liver cancer cell invasion and migration by suppressing HOXA1 expression." (PMID 34277436, 2021).
microtia (4 papers, 2015 to 2024). "Here we first demonstrated that a truncating mutation in HOXA1 causes a monogenic disorder of microtia in pigs." (PMID 26035869, 2015). "This reinforces our assumption that HOXA1 c.451delinsTC is the disease-causing mutation, and suggests that the microtia is a rare disease occurring solely in Shaziling pigs." (PMID 26035869, 2015). "Although there are limitations of our analysis, we have obtained multiple lines of evidence that strongly support the causality of HOXA1 c.451delinsTC in microtia." (PMID 26035869, 2015). "In this study, we identified a truncating mutation (c.451delinsTC) of HOXA1 as a candidate causative variant for congenital microtia in Chinese Shaziling pigs." (PMID 26035869, 2015). "Altogether, we assume that HOXA1 c.451delinsTC causes the microtia and its associated abnormalities in Chinese Shaziling pigs." (PMID 26035869, 2015). "344A>G) in HOXA1 identified in one isolated unilateral microtia patient also attracted our interest." (PMID 28968992, 2017).
ovarian carcinoma (4 papers, 2021 to 2024). A malignant neoplasm originating from the surface ovarian epithelium. "lncRNA HOXA1 can promote the proliferation and migration of ovarian cancer cells, which is closely linked to the prognosis of the ovary." (PMID 34776953, 2021). "HOXA1 was significantly decreased in ovarian cancer cells after transfection with miR-10a-5p mimics, and its overexpression abrogated the effect of miR-10a-5p, leading to a reduction in cell viability and migration." (PMID 38612604, 2024). "For example, in human ovarian cancer cells, miRNA-10a-5p inhibited the viability, colony formation, migration, and invasion ability of human ovarian cancer cells and down-regulated the expression of HOXA1." (PMID 36076940, 2022). "However, when HOXA1 was overexpressed, the inhibitory effect of miRNA-10a-5p on ovarian cancer cells was eliminated." (PMID 36076940, 2022).
thyroid cancer (4 papers, 2020 to 2024). "Other studies have shown the hypermethylation of HOXA1 in cholangiocarcinoma and thyroid carcinoma." (PMID 38473236, 2024).
cholangiocarcinoma (3 papers, 2022 to 2024). A carcinoma that arises from the intrahepatic biliary tree (intrahepatic cholangiocarcinoma) or from the junction, or adjacent to the junction, of the right and left hepatic ducts (hilar cholangiocarcinoma). "Recently, the methylation level of HOXA1 was used to accurately differentiate between cholangiocarcinoma and benign biliary stricture from brushed biliary samples in clinical trial NCT04568512." (PMID 35054365, 2022). "A cfDNA analysis of cholangiocarcinoma patients and healthy sex- and age-matched controls revealed differentially methylated regions (DMRs) in four genes (HOXA1, PRKCB, CYP26C1, and PTGDR) in CCA patients." (PMID 37568696, 2023).
Duane retraction syndrome (3 papers, 2011 to 2021). Duane retraction syndrome (DRS) is a congenital form of strabismus characterized by horizontal eye movement limitation, globe retraction and palpebral fissure narrowing in attempted adduction. "Individuals with simplex isolated Duane syndrome have not been found to harbor pathogenic variants in HOXA1." (PMID 33827624, 2021).
endometrial cancer (3 papers, 2020 to 2024). Primary or metastatic malignant neoplasm involving the endometrium (mucous membrane that lines the endometrial cavity). "In the study of endometrial cancer, high expression of HOXA1 in Myeloid-derived suppressor cells (MDSCs) promotes tumor progression and hinders anti-tumor immune response." (PMID 33763449, 2020).
esophageal cancer (3 papers, 2021 to 2024). A primary or metastatic malignant neoplasm involving the esophagus. "Interestingly, the impact of HOXA1 on esophageal carcinoma can be mitigated through the use of antisense oligodeoxynucleotides, which effectively suppress the invasion and metastasis of esophageal carcinoma cells by inhibiting the activation of the PI3K/AKT signaling pathway." (PMID 38311789, 2024).
lymph node metastasis (3 papers, 2012 to 2023). "Overall mortality was significantly associated with advanced FIGO stage, lymph node metastasis, lymphovascular invasion, and increased HOXA1, HOXA5, HOXA6, and HOXC11 mRNA expression." (PMID 29137433, 2017). "High expression of the HOXA1 gene was also found to be positively correlated with squamous cell histologic type and lymph node metastasis." (PMID 29137433, 2017).
Arthritis (2 papers, 2025). Inflammation of a joint. "Indeed, PARP1 and HOXA1 have been reported as key molecules in IL‐1β‐related inflammatory osteolysis and chondrocyte degradation, respectively, in human diseases such as arthritis." (PMID 40545975, 2025). "In addition to the BACH1 discovery, the highest ranked TFs in RA FLS included two homeobox genes (NKX2-1 and HOXA1) not previously implicated in arthritis." (PMID 39467637, 2025).
autism spectrum disorder (2 papers, 2011 to 2024). A spectrum of developmental disorders that includes autism, and Asperger syndrome. "HOXA1 and HOXB1 have been strongly posed as candidate genes for autism spectrum disorders (ASD) given their important role in the development of hindbrain." (PMID 21980499, 2011).
Cirrhosis (2 papers, 2023 to 2025). A chronic disorder of the liver in which liver tissue becomes scarred and is partially replaced by regenerative nodules and fibrotic tissue resulting in loss of liver function. "The results demonstrate that gender and cirrhosis status are important clinical risk factors for the hypermethylation of HOXA1 and TSPYL5, respectively." (PMID 37835478, 2023). "Through a detailed analysis of the association between cirrhosis status, liver etiology, gender, age, and tumor size with DNA methylation changes, we identified DNA methylation changes in HOXA1-, CLEC11A-, AK055957-, and TSPYL5-associated clinical risk factors." (PMID 37835478, 2023). "Although the individual biomarkers HOXA1, CLEC11A, and AK055957 poorly discriminated between cirrhotic HCC and cirrhosis with 47–60% sensitivity (AUCs 0.52–0.72), the combination of DMMs demonstrated higher AUCs compared to single biomarkers (AUCs 0.84–0.86)." (PMID 37835478, 2023). "In summary, we found that patients with non-cirrhotic HCC exhibited aberrant DNA methylation levels in liver tissue for HOXA1, CLEC11A, AK055957, and TSPYL5 as compared to hepatitis, benign lesions, and cirrhosis." (PMID 37835478, 2023). "Notably, the median methylation scores of HOXA1, CLEC11A, and TSPYL5 were higher in cirrhotic HCC compared to cirrhosis, hepatitis, and benign lesions, although only CLEC11A exhibited a statistical difference (p < 0.05)." (PMID 37835478, 2023). "Although HOXA1 has been reported as a reliable DMM for early HCC detection in cfDNA, we did not identify a specific hypermethylated site for HOXA1 through our genome-wide DMRs analysis of MeD-seq data in the comparison of cirrhotic HCC and cirrhosis tissue." (PMID 40375278, 2025). "Hypermethylation of HOXA1, CLEC11A, AK055957, and TSPYL5 was observed in non-cirrhotic HCC compared to hepatitis and cirrhosis (p < 0.05)." (PMID 37835478, 2023). "In contrast, both MeD-seq and qMSP exhibited no distinct methylation changes in HOXA1 during the comparison of cirrhotic HCC and cirrhosis." (PMID 37835478, 2023). "In summary, the data from MeD-seq confirmed the results of qMSP that non-cirrhotic HCC had the highest methylation levels of HOXA1, CLEC11A, and TSPYL5 compared to hepatitis, benign lesions, and cirrhosis." (PMID 37835478, 2023). "Importantly, and to further support these findings, we also found an increased percentage of DNA methylation in non-cirrhotic HCC compared to hepatitis, benign lesions, cirrhosis, and even cirrhotic HCC samples, such as HOXA1, which was validated by multivariate linear regression analysis." (PMID 37835478, 2023).
Fallot’s tetralogy (2 papers, 2023). "Hoxa1-deficient mice exhibit defects such as interrupted aortic arch, aberrant subclavian artery, and Fallot’s tetralogy, indicating that Hoxa1 is necessary for the formation of major arteries and cardiac outflow." (PMID 37508332, 2023).
mediastinal tumours (2 papers, 2024 to 2025). "HN-PG and the suspected non-chromaffin mediastinal tumours had low expression of the chromaffin cell marker CARTPT24, neural transcriptional regulators (TFAP2B, TOX3, GATA3, POU4F, NEUROG2, PAX2), HOX genes (HOXA1-10, HOXB4, HOXB6-9, HOXC4-HOXC13), and the long non-coding RNA HOTAIR." (PMID 40097403, 2025). "HN-PG and the suspected non-chromaffin mediastinal tumours had low expression of the chromaffin cell marker CARTP24, neural transcriptional regulators (TFAP2B, TOX3, GATA3, POU4F, NEUROG2, PAX2), HOX genes (HOXA1–10, HOXB4, HOXB6–9, HOXC4-HOXC13), and the long non-coding RNA HOTAIR." (PMID 38978571, 2024).
mouth neoplasms (2 papers, 2022 to 2024). "Herein, we studied the methylation pattern of HOXA1 in oral cavity tumors." (PMID 38473236, 2024).
nasopharyngeal carcinoma (2 papers, 2021 to 2022). A carcinoma arising from the nasopharyngeal epithelium. "HOXA1 expression is tended to elevate in nasopharyngeal carcinoma cells and up‐regulating HOXA1 leads to promoted nasopharyngeal carcinoma cell growth and proliferation." (PMID 34514705, 2021). "Moreover, immunohistochemical assays indicated that high HOXA1 expression was significantly correlated with a high recurrence rate of nasopharyngeal carcinoma (NPC) after radiotherapy." (PMID 36119466, 2022).
pancreatic ductal adenocarcinoma (2 papers, 2019 to 2022). An infiltrating adenocarcinoma that arises from the epithelial cells of the pancreas. "Several genes in the 500 kb vicinity of HOXA5 (i.e., HOXA3, HOXA9, HOXA7, HOXA1, EVX1) were also associated with high density lipoprotein (HDL) cholesterol efflux capacity, BMI, and pancreatic ductal adenocarcinoma." (PMID 35836279, 2022).
pneumonia (2 papers, 2024 to 2025). An acute, acute and chronic, or chronic inflammation focally or diffusely affecting the lung parenchyma, caused by an infection in one or both of the lungs (by bacteria, viruses, fungi, or mycoplasma.). "Reducing HOXA1 expression by UCA1 overexpression aggravates the progression of sepsis‐induced pneumonia." (PMID 39713961, 2025). "Lastly, in sepsis-induced pneumonia, the decreased expression of urothelial carcinoma-associated 1 (UCA1) leads to the downregulation of EZH2, consequently increasing HOXA1 expression." (PMID 38311789, 2024). "This upregulation of HOXA1 contributes to the mitigation of sepsis-induced pneumonia progression." (PMID 38311789, 2024).
retinoblastoma (2 papers, 2020 to 2025). A malignant tumor that originates in the nuclear layer of the retina. "In retinoblastoma cells, HOXA1 promotes cell proliferation via the Wnt/β-catenin signaling axis." (PMID 40076953, 2025).
Sepsis (2 papers, 2024 to 2025). Sepsis is defined as life-threatening organ dysfunction caused by a dysregulated host response to infection. "By targeting HOXA1, HOTAIRM1 blockade alleviates lung injury and improves the survival of mice in an in vivo model of sepsis." (PMID 39713961, 2025).
acute adult T-cell leukemia/lymphoma (1 paper, 2019). "The analysis revealed that compared to healthy tissues, HOXA1 mRNA was overexpressed 3.45-fold in AML and 10.08-fold in acute adult T-cell leukemia/lymphoma (ATLL)." (PMID 31426381, 2019).
anencephaly (1 paper, 2019). A rare neural tube defect during pregnancy, resulting in the absence of a large portion of the brain and skull in the fetus. "To investigate the potential effect of expression levels of the selected HOX genes (HOXA1, HOXA7, HOXA9, HOXA10, HOXB1, and HOXB7) in anencephaly, we evaluated 10 anencephaly cranial tissues and 10 matched normal fetus cranial samples by the NanoString technique." (PMID 30992047, 2019).
atrioventricular septal defects (1 paper, 2020). "The addition of progenitor cells from the pSHF to the venous pole is also impaired in Hoxa1-/-; Hoxb1-/- hearts, resulting in abnormal development of the DMP and consequent atrioventricular septal defects (AVSDs)." (PMID 32804075, 2020).